MMP10 (matrix metallopeptidase 10)
Diseases named in the same sentence as MMP10 in open-access papers (continued):
Sharing a sentence is not in itself a finding about the gene and the disease.
tumor (continued). "Beyond that, a study showed that GADD45A promotes Myc-driven breast carcinogenesis by negatively regulating matrix metalloproteinase 10 (MMP10) through GSK-3β (Glycogen synthase kinase 3 beta)/β-catenin signaling, resulting in increased tumor vascularization and growth." (PMID 30128181, 2018). "In relation to serum MMP-10, its potential as a tumor marker for NSCLC diagnosis has not been earlier addressed, to our knowledge." (PMID 29207990, 2017). "Moreover, MMP-10 up-regulates several other MMPs such as MMP-1, MMP-7, MMP-9, and MMP-13 that are essential for tumor progression." (PMID 27271600, 2016). "Though other MMPs (e.g., MMP-1, -2, -8, -9, -13) have been linked to degradation of laminin, vitronectin, fibronectin, enactin, collagen I-IV, MMP-10 has been identified as a stromelysin which can degrade various proteoglycan components of the ECM, thus facilitating tumor cell dissociation." (PMID 24885595, 2014). "Our data are consistent with numerous reports that Mmp10 is expressed in human NSCLC cells and not surrounding normal or tumor-associated lung tissues." (PMID 22545096, 2012). "44/50 stem cell signatures were enriched in high Mmp10 tumor samples and none were enriched in the low Mmp10 tumor samples from this second data set." (PMID 22022614, 2011). "For MMP-10, nuclei and cytoplasm of tumor cells were positive, whereas no staining was found for stromal and immune cells." (PMID 19531263, 2009). "Of importance, not all the EV protein cargo reflected the transcriptional effects induced by TGF-β, as noted for NOG, ITGB5 and MMP10, suggesting that sorting of different cargo proteins into tumor-derived EVs does not strictly follow the abundance of the respective mRNA." (PMID 39910665, 2025). "Importantly, MMP-10 expression is not found in physiological ovarian tissue; it is only confirmed in tumour tissue." (PMID 40565125, 2025). "However, the expression of pro-tumorigenic genes including Ang4, VEGF, Wnt5a and MMP-10 was comparable in the LRRK2 KI and WT control groups, suggesting that LRRK2 G2019S may promote tumor development primarily by promoting inflammation." (PMID 38607004, 2024). "We could see that about half MMPs are highly expressed in tumor tissues as compared with normal tissues, including MMP9, MMP10, MMP11, MMP12, MMP15, MMP25, MMP26 (all, P<0.05), while some other MMPs decreased in tumor tissues, including MMP2, MMP14, MMP16, MMP24, MMP28(all, P<0.05)." (PMID 32669958, 2020). "Moreover, MMP7, MMP13, and MMP10 were significantly upregulated in metastatic tumour samples compared with nonmetastatic tumour samples." (PMID 31996191, 2020). "However, when HeLa cells were grown in a 3D matrix (data not shown), or as a xenograft tumor, MMP-10 expression was induced." (PMID 24885595, 2014). "MMP-10 (also known as stromelysin 2) is generally limited to epithelial cells and can target pro-MMP-1, -7, -8, -9, -13, collagen type III, IV, V, gelatin, elastin, fibronectin, proteoglycans and laminin, activities that have been shown to promote tumor cell invasion." (PMID 24885595, 2014). "MMP-10 degrades ECM components, including collagen III, collagen IV, gelatin, casein, laminin and proteoglycan elastic hard protein, which is considered to be an important activating factor in human tumor cells that may be activated in other pro-MMPs." (PMID 25009646, 2014). "Interestingly, when Mmp10−/− mice were exposed to urethane, these mice developed significantly fewer and smaller tumors, and exhibited a smaller total tumor burden than non-transgenic (NTg) littermates." (PMID 22022614, 2011). "However, we cannot formally rule out an additional role for Mmp10 in bulk tumor cells that contributes to the metastatic potential of tumors." (PMID 22022614, 2011). "However, our data do not exclude a contributory role for Mmp10 produced by and/or exerting its effects upon the tumor microenvironment." (PMID 22022614, 2011).
tumor (continued). "In addition, expression of molecules involved in ECM remodeling such as several metalloproteinases (MMP2, MMP9, MMP10 and MMP13), serine protease (PLAU) collagens, fibronectins and integrins indicate that functional EMT transition and metastasis take place within the tumor microenvironment." (PMID 34946170, 2021). "The authors proposed as a mechanism the altered lung microenvironment by the primary tumor through the local expression of vasopermeability factors, namely Angpt 2, MMP3, and MMP10, but not VEGF." (PMID 40435350, 2025). "Intriguingly, these observations were almost further validated by our real‐time qPCR results of five pairs of tumor and adjacent nontumor samples, such as COL1A1, MMP1, MMP10, CXCL8, and IL1B." (PMID 34821009, 2022). "MMP7, MMP13, and MMP10 were significantly upregulated, while MMP12 and MMP9 were downregulated in metastatic tumour samples compared with nonmetastatic tumour samples." (PMID 31996191, 2020). "In conclusion, VEGF-A, MMP-10, and CXCL6 share features of non-functional, anti-inflammatory tumor-promoting markers that may be induced upon selected stimuli." (PMID 31824496, 2019). "Mmp 10 is highly expressed in NSCLC tumors, but not in surrounding tumor stromal cells." (PMID 30060526, 2018).
cancer (99 papers, 2001 to 2026). A tumor composed of atypical neoplastic, often pleomorphic cells that invade other tissues. "MMP-10 expression has been implicated in the modulation of invasion, apoptosis, angiogenesis, and cell proliferation in cancer." (PMID 36505884, 2022). "Further analyses are required in order to clarify the association of MMP-10 in cancer prevention and treatment by curcumin." (PMID 24531055, 2014). "A similar association of Mmp10 expression with metastatic lesions in human cancers was observed when we analyzed publicly-available gene expression datasets of human tumors using the NextBio bioinformatics tool." (PMID 22545096, 2012). "Studies have linked MMP-10 to cancer stem cell viability, tumorigenesis and metastasis." (PMID 40935823, 2025). "Furthermore, we analyzed the potential correlations of these proteins with MMP-10 expression by utilizing the Cancer Dependency Map, a comprehensive database for loss-of-function screening encompassing hundreds of cancer cell lines." (PMID 40382334, 2025). "Enhanced MMP-10 expression has been linked to poor clinical prognosis in some cancers, however, mechanisms underlying a role for MMP-10 in tumorigenesis and progression remain largely unknown." (PMID 24885595, 2014). "Our findings reveal that MMP-10 expression can induce the expression of key molecules implicated in angiogenesis, metastasis and apoptosis, major mechanisms involved in the establishment and progression of malignant tumors." (PMID 24885595, 2014). "Validation of the association between high Mmp10 in lung tumors and cancer stem cell signatures." (PMID 22022614, 2011). "We then performed gene set enrichment analysis (GSEA) against gene sets available as part of the Molecular Signatures Database (MSig) Version 3.0 as described in Materials and Methods to measure any association between Mmp10 and cancer stem cell gene expression profiles." (PMID 22022614, 2011). "In our study, we found the highest concentrations of MMP-10 in patients with benign lesions (208.80 pg/mL) compared to cancer patients (160.35 pg/mL) and healthy women (59.51 pg/mL)." (PMID 41007705, 2025). "Furthermore, SFV infection of cancer cells downregulated several migration- and invasion-associated genes in macrophages (e.g., Mmp8, Mmp10 and Mmp12), particularly in the SFV/IFNγ group, suggesting that this approach may inhibit cancer cell dissemination and metastasis." (PMID 40547518, 2025). "Unfortunately, our study did not yield statistically significant analyses of tested MMP-3 and MMP-10; however, our work focuses only on the early stages of cancer." (PMID 40332487, 2025). "Both these results accord with maximum expression of MMP10 in the early stages of cancer, reaffirming the effectiveness of our study design in identifying stage-salient markers." (PMID 41048341, 2025). "Our analysis revealed a complex interaction between TIMP1 and MMP10, suggesting their pivotal roles as central nodes in both coagulation and cancer pathways." (PMID 40777024, 2025). "MMPs of the matrilysin (MMP-7 and MMP-26) and stromelysin (MMP-3 and MMP-10) groups also play an essential role in cancer pathogenesis." (PMID 40332487, 2025). "MMP-10, a neurodegeneration marker belonging to the stromelysin family, is elevated in positive cases of COVID-19 in individuals with cancer." (PMID 37372128, 2023). "Transcriptome analysis revealed that CHRM3 knockdown significantly reduced an array of classic factors in cancer invasive growth including MMP1/MMP3/MMP10/MMP12 and CXCL1/CXCL5/CXCL8." (PMID 37744266, 2023). "A significantly lower content of MMP-3 in both cancer grades in contrast to the distinctive growth of MMP-10 was observed." (PMID 36231910, 2022). "PCA loadings show that the genes exerting the largest effects include MMP1 and MMP10, KRT7, and KRT19, high levels of which in other cancers have been associated with unfavorable prognosis." (PMID 35480116, 2022).
cancer (continued). "MMP 3 and MMP 10 have been established as typical MMPs involved in metastatic properties of cancer cells." (PMID 36172283, 2022). "For example, MMP1, MMP3 and MMP10 have been found to promote cancer cell initial invasion and distant dissemination." (PMID 36324128, 2022). "Cancer cells of the invasive front strongly express MMP-10, and the majority of sarcomatous cancer cells shows moderate or strong intensity." (PMID 35216251, 2022). "These two targets have a few interacting proteins in common such as TIMP (1, 2 and 3), STAT 3, VEGF A, SRC, DCN, MMP 10 and CD 44 and all are supposed to be plum targets for cancer therapies." (PMID 34075089, 2021). "MMP-10 prevails over MMP-3 also in cancer tissues, but the MMP-10 content was similar in high-grade and low-grade tumors." (PMID 34441979, 2021). "Since MEF2C nuclear translocation was reported to promote the transcription of its target genes vegf and mmp10, MEF2C seems to have an important role in cancer-associated signaling pathways." (PMID 33673112, 2021). "The determined differences in actual activity of MMP-10 between both cancer grades and control tissue were significant (p < 0.001)." (PMID 34441979, 2021). "Although PTHLH, MMP1 and MMP10 were mainly up-regulated in the 21 cancer types, the rest of the members GATM and ARHGEF26, were primarily down-regulated with a few exceptions." (PMID 34301206, 2021). "The content of MMP-10 was significantly lower in control tissue in comparison to low-grade and high-grade cancer tissues (p < 0.001 for both)." (PMID 34441979, 2021). "Activation of MMP10 has been previously reported to stimulate cancer cell proliferation, migration and metastasis." (PMID 33713583, 2021). "The other stromelysins, MMP3 and MMP10, were significantly upregulated in 7 cancer types and 10 cancer types respectively." (PMID 31200666, 2019). "Incidentally, MMP10 is known to be involved in promoting metastases and inflammation in other cancers." (PMID 28939077, 2017). "Regarding MMP-10, over-expression in cancer-initiating or cancer stem cells is key on their maintenance and tumorigenic potential, allowing for lung tumor-initiating activity and metastatic spread." (PMID 29207990, 2017). "MMP10 is expressed only in cancers and in the uterus among normal organs as estimated by analysis using an online database (biogps.org)." (PMID 27072580, 2016). "This Aurora-A-FLJ10540-MMP-7/MMP-10 axis is involved in cancer cell proliferation, migration, invasion and chemoresistance." (PMID 25889801, 2015). "We then examined the influence of EGF on MMP9 transcription as well as on the transcription of additional MMPs (MMP-1, MMP-2, MMP-3, MMP-7, MMP-10, MMP-13, MMP14, MMP15) and of CD44, a cell adhesion glycoprotein implicated in EMT and cancer metastasis." (PMID 26084289, 2015). "We found that orospheres overexpressed several genes, such as VEGF, FXYD5 (dysadherin), CXCR2, and MMP10, that have been strongly correlated with invasion and metastasis in many cancers, including H&N carcinomas." (PMID 25428916, 2015). "Based on our previous observations, we noted that the expression of Mmp3, Mmp10, and Mmp13 was dramatically increased from inflammation to cancer, particularly during acute inflammatory stage (~200-fold increase)." (PMID 25742789, 2015). "Samples were semiquantitatively assessed by scoring the intensity of the staining and the proportion of MMP-10-positive cancer cells." (PMID 24885595, 2014). "Tongue carcinoma cells treated with curcumin, a naturally occurring polyphenol derived from the root of Curcuma longa, inhibited cancer invasion through the suppression of MMP-10 expression." (PMID 24531055, 2014). "To determine the potential relevance of MMP10 in human cancer we analyzed Mmp10 expression in publicly-available gene expression profiles of human cancers." (PMID 22022614, 2011).
cancer (continued). "GSEA revealed that 37 of the 50 (74%) cancer stem cell signatures were enriched in the high Mmp10 samples, and that 14 signatures were significantly enriched with a p-value <0.05 and FDR <25%." (PMID 22022614, 2011). "Gelatin zymography showed bands corresponding in size to MMP-2, MMP-3, MMP-9, and MMP-10 enzymes in each of the 24 cancer cases." (PMID 20920372, 2010). "Among these genes, the most overexpressed in platelet-educated cancer cells are those encoding proteins involved in cancer progression and metastasis, including SERPINE1 (358%), MMP2 (297%), MMP10 (214%), TIMP1 (187%), FN1 (166%), TMPRSS4 (146%) and RHOC (102%)." (PMID 40096084, 2025). "This may also indirectly confirm the theory that high expression and concentrations of MMP-10 may be associated with and correspond to, just like MMP-7, an increase in cancer progression." (PMID 41462922, 2025). "Further research is needed to elucidate how MMP-10 may impair neurological function following COVID-19 infection in cancer patients." (PMID 37372128, 2023). "MMP-10 plays an important role in the development and progression of malignant tumors." (PMID 36505884, 2022). "In addition, the content of MMP-10 in the control tissue, low-grade cancer and high-grade cancer was higher in comparison to MMP-3." (PMID 34441979, 2021). "The narrow band of 202 kDa visible for MMP-10 in the high-grade cancer may only be an enzyme in complexes." (PMID 34441979, 2021). "Interestingly, MMP-10 is expressed in infections, in response to injury and in cancer transformation." (PMID 33371324, 2020). "Interestingly, several genes associated with cancer cells invasion were downregulated upon HPSE knockdown, including MMP1, MMP7, MMP10, MMP13, and CEACAM6." (PMID 31001480, 2019). "Previous reports indicated that the epigenomics changes of MMP10, especially DNA methylation may be involved in the occurrence of cancer." (PMID 29933410, 2018). "MMP-10 is one of the most well-known MMPs involved in the pathogenesis of carcinomas." (PMID 26415518, 2015). "Mmp10 expression correlates with metastasis in human cancer types." (PMID 22545096, 2012). "However, little is known about involvement of MMP-10 in the invasion and metastasis of cancer cells." (PMID 21998657, 2011). "Elevated levels of MMP-10 may likely induce the expression of crucial molecules involved in angiogenesis, metastasis, and apoptosis, fostering a favourable environment that supports the survival and growth of malignant tumours." (PMID 38032961, 2023). "To further generalize our findings, we used LPS to stimulate murine macrophages (RAW264.7) to imitate inflammation and measured Mmp3, Mmp10, and Mmp13 expression over time; the mRNA levels were significantly increased, indicating that these three genes are upregulated in inflammation-cancer link." (PMID 25742789, 2015). "Among the 22 investigated MMPs, seven genes (MMP2, MMP3, MMP10, MMP12, MMP14, MMP15, and MMP16) were upregulated in cancer, while MMP8 was downregulated." (PMID 41728806, 2026). "Studies have widely reported that KRT4, IGFBP3, MMP10, MMP3, and TGFBI are involved in the pathogenesis of LC and other cancers." (PMID 38302910, 2024). "MMP1, MMP3, and MMP10 are highly expressed in HNSCC, compared to other cancers by analyzing the data of Oncomine and GEPIA databases." (PMID 38302910, 2024). "For MMP10 and NR0B1, their positive correlation or positive correlation trend with the anti-cancer drugs suggested HCC resistance to the drugs." (PMID 38374122, 2024). "MMP10, a member of the matrix metalloproteinase (MMP) family, is involved in vascular development and lumen formation to promote cancer cell growth and migration." (PMID 38833118, 2024). "Meanwhile, we noted that Matrix Metalloproteases (MMPs), including MMP1, MMP3, MMP7, MMP10 and MMP13 genes were significantly upregulated in the BSE group, and they were almost universally upregulated in cancer." (PMID 37697300, 2023).